CD163 (CD163 molecule)
Diseases named in the same sentence as CD163 in open-access papers (continued):
Sharing a sentence is not in itself a finding about the gene and the disease.
breast carcinoma (continued). "Moreover, CD163+ macrophages involved in the angiogenic response and immunosuppression are more numerous as compared to M1 subset, confirming their pro-tumorigenic role in breast cancer." (PMID 29854311, 2018). "Though the expression of M2 macrophage-specific antigen CD163 varied significantly in primary breast cancer, its prevalence has a prognostic impact on both relapse-free survival and overall survival, which could be explained by fusion between macrophages and cancer cells." (PMID 22848668, 2012). "CD163+ macrophages in tumor stroma positively correlated with higher grade, larger tumor size, Ki67 positivity, estrogen receptor negativity, progesterone receptor negativity, triple-negative/basal-like breast cancer and inversely correlated with luminal A breast cancer." (PMID 22824040, 2012). "M2 CD163+ and CD68+ macrophages are more abundant in TNBC/basal-like breast cancer than luminal types." (PMID 40141437, 2025). "Immune infiltrating cells in breast cancer were identified using antibodies to CD20 (B-cells), CD3 (T-cells), and CD163 (macrophages)." (PMID 41294872, 2025). "Subsequently, we evaluated the impact of CD68, CD163, CD86, and PD-L1 expression in primary tumor tissues on overall survival, defined as the time from the initial breast cancer diagnosis to death." (PMID 40510346, 2025). "Specifically, the authors assessed the status of PD-L1, PD-1, CTLA-4, CD68, CD163, CD11c, iNOS, CD3, CD8, CD4, FOXP3, CD20, and Ki67 along with pan Cytokeratin and CD31 in the TME of 3098 tumors, including 587 cases with breast cancer." (PMID 40243442, 2025). "This study highlights the prognostic importance of Trop-2, CD47, and CD163 expression in TNBC, an aggressive and treatment-resistant subtype of breast cancer." (PMID 39857116, 2025). "On the contrary, a recent study suggests that higher densities of CD163+ macrophage infiltration TNBC tumors improved overall survival and breast cancer-specific survival independently in invasive TNBC." (PMID 40141437, 2025). "Next, we compared the expression of 27 primary breast cancers and their paired brain metastases for CD68, CD163 and CD86." (PMID 40510346, 2025). "Combined analysis demonstrated that breast cancer patients with CD8 (low) and CD163 (high) as well as CD8 + TCF1 + (low) and CD163 (high) levels were associated with worse DFS (p < 0.0001 and p = 0.00023, respectively)." (PMID 38349444, 2024). "Higher AF of CD163 vs. CD68 agrees with the observations in HCC, liver metastasis of colorectal cancer, and breast cancer." (PMID 38287290, 2024). "Here, we show that a subpopulation of CD163+ TAMs proliferates in situ within the TME of melanoma, lung cancer, and breast cancer." (PMID 38903497, 2024). "Breast cancer tissues in TMA were utilized to investigate the clinical significance of CXCL1 and its relevance with HMGB1, IGF1R, and CD163 expressions." (PMID 39394189, 2024). "By analyzing FABP4 expression in TAMs with human breast cancer specimens, we found that FABP4 expression in TAMs, especially CD163+ TAMs, correlated directly with tumor size, grade, metastasis and even patient survival." (PMID 39513934, 2024). "The spatial distribution and interactions with TILs enhanced the prognostic value of CD163 TAMs, while CD206 TAMs appeared to have limited prognostic utility in breast cancer cases." (PMID 38893266, 2024). "In the present study, we focused on the prognostic role of M2 TAMs (CD163+) and all TAMs (CD68+) in early breast cancer according to HER2 status and hormone receptor status." (PMID 38339385, 2024). "Our results also showed that a subpopulation of CD163+ TAMs proliferates within the TME of melanoma, lung cancer and breast cancer." (PMID 38903497, 2024). "Others reported that high expression of CD68, CD163 and CD206 was predictive of poor OS, breast cancer-specific survival, or recurrence-free survival." (PMID 36622544, 2023).
breast carcinoma (continued). "Perhaps CD163+ cells represent a dysfunctional or exhausted macrophage population that lost CD16 expression, as has been reported in breast cancer and other pathologies." (PMID 38318505, 2023). "Jeong and colleagues found that a high number of CD163+ macrophages within tumor nests was an independent prognostic marker of reduced OS and DFS in 367 breast cancer patients." (PMID 35053472, 2022). "Prior studies have demonstrated an expansion of the CD163-expressing, M2-like macrophage population in the TME of breast cancer patients, with a high intra-tumoral density of these cells being associated with decreased survival." (PMID 35677046, 2022). "Patients with either high levels of HLA-DR or TILs, or high activation score of MHC-II, or low level of CD163+ TAMs, as well as high expression level of FZR1, had better response to NACT in breast cancer." (PMID 35877249, 2022). "Some studies reported CD163 and CD68 co-localization in macrophages, including in breast cancer, in agreement with our observations." (PMID 36230752, 2022). "We subjected 81 breast cancer specimens to immunostaining for CD68, CD163, PD-1, PD-L1, CD20, and pan-CK." (PMID 36362023, 2022). "M1 markers (CD80 and CD86) showed a better correlation with markers of endothelial activation compared with total macrophage marker (CD68) and with M2 markers (CD163 and CD206) in breast cancer samples." (PMID 36248978, 2022). "After being cultured with breast cancer MDA-MB-453 cell-conditioned medium, macrophages were inclined to the M2 phenotype (IL-10 high, TGF-β high, CD163 high, CCL-17 high, CCL-22 high) in the circWWC3-transfected group as compared to the control group." (PMID 35996149, 2022). "In order to further pinpoint the role of TAMs in microcalcifications of breast cancer cells, THP-1 cells were treated with PMA and IL-4 to induce differentiation into M2-like TAM which was verified by CD68 and CD163 expression (M2-like phenotype biomarker)." (PMID 34983451, 2022). "CD163 and CD204 are relatively specific markers for M2, the breast cancer infiltration of CD163 positive and CD204 positive TAMs tends to have a poor prognosis as these TAMs are associated with fast proliferation, poor differentiation." (PMID 35237507, 2022). "CD209, CD163, CSF1, and MMD were related to M2 macrophage proportions in cutaneous melanoma, breast carcinoma, head and neck squamous cell carcinoma, hepatocellular carcinoma, prostate cancer, renal cancer, and lung adenocarcinoma." (PMID 33828973, 2021). "Lindstrom and colleagues co-cultivated human M2-macrophages and GFP-labeled MCF-7 human breast cancer cells and spontaneously formed GFP+, CD163+, and CD45+ tumor hybrids were sorted by flow cytometry." (PMID 34503305, 2021). "Breast cancer patients with gene expression signatures that were high for both DEK and CD163 showed decreased overall survival (OS), distant metastasis-free survival (DMFS), and especially relapse-free survival (RFS)." (PMID 32708944, 2020). "In vivo, we demonstrate in both this clinically relevant murine model and in human breast cancers that DEK expressing tumors regulate a similar pattern of immunomodulatory genes identified in our ex vivo cell culture model and contain CD163+ M2-like TAMs." (PMID 32708944, 2020). "In this study, to explore the representative characters of TAMs among subtypes of human breast cancer in depth, we focused on studying protumor TAM markers among human breast cancer tissues: CD163, CD204, CD206, which are commonly used in mouse models." (PMID 31799941, 2019). "We have previously reported infiltrating macrophages in adipose stroma of breast cancer recognized by CD68 and CD163 IHC, and the results of the previous study were used to analyze this relationship with the expression of ATX-LPA signaling-related proteins." (PMID 31035435, 2019).
breast carcinoma (continued). "We analysed the presence of macrophages positive for CD163 and CD206 as well as α-SMA positive fibroblasts in 50 human breast cancer samples using immunohistochemistry." (PMID 30816272, 2019). "In the present comprehensive meta-analysis, we report that both CD68- and CD163-positive macrophages are significantly associated with poor prognosis, advanced histological grade, high Ki67 expression and negative hormonal receptor expression in early stage breast cancer." (PMID 31528210, 2019). "Here, we have objectively and simultaneously measured in situ the expression of TAM biomarkers (CD68, CD163, and the druggable target MMP-9) in two distinct breast cancer cohorts by using the validated quantitative immunofluorescence (QIF) AQUA method." (PMID 30558648, 2018). "ER is amongst the most important biomarkers for breast cancer; thus, all three TAM biomarkers (CD68, CD163, and MMP-9) are examined in the context of ER status." (PMID 30558648, 2018). "In our study, the breast cancer tissue samples tested had increased T cell and macrophage immune cell marker (CD4, CD25, CD63, CD163) expression compared to benign tissue." (PMID 26964534, 2016). "Based on our knowledge, this is the first study that demonstrated the expression of CD163 in cancer cells and its correlation with poor prognosis in OSCC, which is consistent with the studies in breast cancer, colorectal cancer and malignant melanoma." (PMID 26769084, 2016). "To explore the clinical relevance of TAM differentiation in breast cancer patients, we evaluated total TAM number (CD68), M1 TAM (HLA-DRα) and M2 TAM (CD163) in a large human breast cancer TMA cohort." (PMID 26243145, 2015). "In breast cancer, the tumor stroma was infiltrated by CD163+ and CD68+ macrophages, CD163+ macrophages positively correlated with higher grade and larger tumor size, and CD68+ macrophages positively correlated with tumor size." (PMID 24883329, 2014). "CD163+ and CD68+ cells with a macrophage-morphology were present in both TS and TN of primary breast cancers." (PMID 22824040, 2012). "CD163+ and CD68+ macrophages were more equally distributed among the patients with luminal A breast cancer." (PMID 22824040, 2012). "We also analyzed the prognostic value of the localization of CD163+ and CD68+ myeloid cells in human breast cancer." (PMID 22824040, 2012). "Kaplan Meier analysis and Cox proportional hazards modeling were used to assess the impact of CD163+ and CD68+ myeloid cells in tumor stroma and tumor nest, respectively, on recurrence free survival, breast cancer specific and overall survival." (PMID 22824040, 2012). "In HER2+ breast cancer, high CD163+ TAM counts predicted worse survival regardless of trastuzumab use, emphasizing the immunosuppressive role of M2-macrophages in therapy-resistant cases." (PMID 41550427, 2025). "We also observed an enrichment in CD163+/CD204+/CD206low immunomodulatory macrophages whose role in breast cancer metastasis has not been studied." (PMID 39437149, 2025). "The prognostic effect of the CD163+ TAM count in HER2+ breast cancer was evident regardless of the administration of adjuvant trastuzumab." (PMID 38339385, 2024). "Increased CD163 + infiltration is associated in most studies with dismal prognosis in breast cancer patients, although there is no consistency on the prognostic impact of CD163 + density among different breast cancer subtypes." (PMID 38349444, 2024). "In this study, we compared the features of CD163 and CD206 TAMs in breast cancers." (PMID 38893266, 2024). "A lower number of CD163+ cells were detected in the mammary tumors of 2‐ME treated mice compared to controls, while no change was observed in the lungs." (PMID 38600057, 2024). "To our knowledge, we are the first who compared CD68, CD163, CSF-1R and CD206 for TAM detection and assessed their relation with clinicopathological characteristics in a large well-characterized series of intrinsic breast cancer subtypes." (PMID 36622544, 2023).
breast carcinoma (continued). "In addition, we confirmed that there were positive correlations among CD163 (TAM marker) expression, ZEB1 expression and DNMT1 expression in breast cancer patient tissues." (PMID 36273188, 2022). "In breast cancer, THP-1 treated with CM from MCF-7 or MDA-MB 231 cells results in the differentiation of THP-1 cells toward macrophages and increases the mRNA expression of M2-type macrophage markers, including CD163 and IL-10." (PMID 35960749, 2022). "The prognostic values of CD163+ TAM density and spatial proximity to breast cancer cells may also be independent prognostic factors in other solid malignancies." (PMID 35053472, 2022). "CD68 and CD163 have been broadly used to show that high TAM density correlates with a worse clinical outcome in breast cancer but do not predict their functional phenotype." (PMID 33968034, 2021). "It was demonstrated that CD163 is predominantly expressed on CD14+CD68+ monocyte-derived macrophages, which infiltrate tumor mass, indicating that NAC can induce the recruitment of CD163+ monocytes into breast cancer tumor." (PMID 35237501, 2021). "Our study has major strengths, including the use of analytically validated antibodies, predefined scoring criteria (CD163 and CAIX), and the use of an independent cohort (cohort I) to confirm the performance of G-CSF as a biomarker on breast cancer tissue microarrays." (PMID 33804486, 2021). "Additionally, more CD163+ macrophages could be detected in triple-negative breast cancer (TNBC) than in other BC subtypes." (PMID 33849622, 2021). "Notably, two representative M2 markers, CD163 and CD206, were increased after treatment with the CM from breast cancer cells, especially the triple-negative breast cancer cell MDA-MB-231." (PMID 33256011, 2020). "Upregulation of CD163, CAMP, P2X7 in macrophages cultured in conditioned medium or co-cultured with cancer cells strongly suggested a positive feedback loop between TAMs and breast cancer cells." (PMID 32365569, 2020). "When we analyzed associations between fatty acid groups and subsequent breast cancer risk by tumor tissue expression subtype, no convincing evidence of heterogeneity was observed by CD4, CD20, CD163, or COX-2 expression." (PMID 32698885, 2020). "Moreover, BASEscope analysis of our cohort of breast cancer showed expression of SIGLEC9 within the stroma, edge and nest of the tumour in a similar manner to CD163 staining." (PMID 33149188, 2020). "Analysis of the TCGA breast cancer database shows a highly significant correlation between CD163 or CD68 and SIGLEC9 but not with the epithelial markers, EPCAM or KRT8." (PMID 33149188, 2020). "For example, the macrophage-specific factors DAP12 and CD163, both of which are not detectable in breast cancer cells, are expressed in fused hybrid breast cancer cells." (PMID 33322354, 2020). "Associations between fatty acids and breast cancer risk did not vary substantially by tumor CD4, CD20, CD163, or COX-2." (PMID 32698885, 2020). "After co-culturing human breast cancer cell lines (MDA-MB-231, MDA-MB-468, and MCF-7) with PMA-induced human monocyte THP-1 cells for 48 h, we found that either STAT3 knockdown or JAG1 knockdown in breast cancer cells reduced the relative mRNA levels of CD206 and CD163 in THP-1 derived macrophages." (PMID 32943090, 2020). "Several studies reported that HER2+ breast cancer has more TAM infiltration (CD68-positive 10, 16; CD163-positive 9, 14, 16), while the majority of the included studies failed to reveal a significant relationship between HER2 expression and TAMs in breast cancer." (PMID 31528210, 2019). "The infiltration of CD163+ TAMs seemed to be the highest in triple negative, and the lowest in ER+PR+ breast cancer samples, although such findings were not statistically significant." (PMID 30816272, 2019).
breast carcinoma (continued). "In our own data, we also found that the ratio of CD163- to CD68-positive macrophages was higher in high histological and Ki67 index breast cancer, where the proportion was nearly 80% in the HR-negative subtype and only about 40% in the HR-positive subtype (data not shown)." (PMID 31528210, 2019). "Subsequent analysis using a publicly-available dataset revealed that the coordinated low-expression of CD163 and CXCR4 with high expression of THBS1 in 161 breast cancer tissues identified patients with TNBC (basal) having a high risk of recurrence and poor survival rate." (PMID 30254632, 2018). "The aims of this study were to objectively determine the in situ expression and significance of TAM biomarkers (CD68, CD163, and MMP-9) in breast cancer and to identify subclasses of patients who could benefit from TAM-targeting therapies." (PMID 30558648, 2018). "(E) Regression of two CD163 antibodies (CD163-L-U, D6U1J) QIF scores in breast cancer TMA." (PMID 30558648, 2018). "CD163-expression ≤ 15% correlated neither with breast cancer-related death nor other clinicopathological data." (PMID 29725763, 2018). "CD8+ and CD163+ cells have prognostic impact in breast cancer but their spatial heterogeneity has not been extensively explored in this type of cancer." (PMID 28428887, 2017). "Immunofluorescence revealed a barely detectable immunostaining of CD68 in CAFs and NHDFs meanwhile no expression can be detected for CD163 and F4/80 markers in CAFs and in NHDFs, ruling out that the cells prepared from breast cancer tissue are not macrophages." (PMID 28178651, 2017). "According to our data, triple-negative/basal-like breast cancers seem to harbor more CD163+ than CD68+ cells within the TS." (PMID 22824040, 2012). "One explanation for the difference between the presence of CD163+ and CD68+ macrophages in TS among triple-negative/basal-like breast cancer patients could be that CD68 is less expressed on mature M2 macrophages or monocytes." (PMID 22824040, 2012). "Although CD163+ macrophages in TS correlated with triple-negative/basal-like breast cancer it did not confer a prognostic value in this group." (PMID 22824040, 2012). "Notably, using the same breast cancer TMA as in this study, GRN expression was found to correlate with the same clinicopathological features as CD163+ macrophages in TS as well as with the density of CD163+ macrophages in TS." (PMID 22824040, 2012). "Additionally, mIHC analysis of the breast cancer tissue microarray confirmed that CD8+ T cell, CD68+ (M0-like) macrophages, and CD68+CD163- (M1-like) macrophages infiltration levels were significantly higher in the LMF_index low group compared to the LMF_index high group." (PMID 40612672, 2025). "While our study sample exceeds that of several prior studies of CD163 in relation to breast cancer prognosis, it is nonetheless not as large as some of the more well-characterized T cell populations like CD8+ T cells, and our findings need to be replicated in additional cohorts." (PMID 38720366, 2024). "However, the number of CD163+ macrophages was lower in mammary tumours, which does not support the findings considering the phenotypic characteristics of higher tumour progression and increased tumour mass." (PMID 37649158, 2023). "High CD163+ TAMs could be used as a promising prognostic biomarker in non-metastatic breast cancer to predict poor NACT response." (PMID 35877249, 2022). "IGF1R signaling negatively impacts immune surveillance in breast cancer patients, as evidenced by IGF1R phosphorylation resulting in slight CD8+ CTL infiltration, significant infiltration of FOXP3+ regulatory T cells, immunosuppressive CD163+ macrophages, and poor prognosis." (PMID 35463082, 2022). "In addition, in multivariable models of CD8, CD4, CD163, and GeparSixto scores, both HER2 and TNBC status significantly contributed to each model reinforcing the importance of investigating TME metrics within specific breast cancer subtypes." (PMID 36376974, 2022).